IGF1 (insulin like growth factor 1)
Diseases named in the same sentence as IGF1 in open-access papers (continued):
Sharing a sentence is not in itself a finding about the gene and the disease.
endometriosis (continued). "So increased IGF-1 levels in the peritoneum of these patients appear to be involved in the pathogenesis of endometriosis, and in particular, in infertility." (PMID 34930225, 2021). "An increase in the serum levels of IGF-1 in women with stages III-IV endometriosis was observed compared to women with stages I-II endometriosis, but it was not statistically significant." (PMID 34930225, 2021). "One study revealed an increased IGF-1 gene and protein expression in EESCs of patients with endometriosis." (PMID 34930225, 2021). "Previous studies consistent with ours showed increased concentrations of IGF-1 in serum and PF in patients with endometriosis compared with controls." (PMID 34930225, 2021). "We demonstrated that the probable source of IGF-1 is PFMCs and EESCs in women with endometriosis resulted in increased levels of this factor in PF and the uncontrolled growth of EESCs." (PMID 34930225, 2021). "Endometriosis-associated macrophages (EAMs) express elevated levels of insulin-like growth factor 1 (IGF1) and elevated concentrations of IGF1 in the peritoneal fluid of patients correlated with the intensity of endometriosis pains." (PMID 34068967, 2021). "The expression level of insulin‐like growth factor‐1 (IGF‐1) has been reported to be significantly different in stages I‐II‐IV and I‐II of endometriosis, but subsequent studies have added much controversy for its use as a biomarker." (PMID 32960511, 2020). "Concentrations of IGF-1 were elevated in peritoneal fluid from women with endometriosis and positively correlate with their pain scores." (PMID 31291762, 2019). "Reportedly, OCT4 is regulated by IGF-1, which suggests that IGF-1 is a critical niche factor for disease progression to an advanced stage of endometriosis." (PMID 31505803, 2019). "IGF-1 present in the PF is thought to play a role in the pathophysiology of endometriosis by stimulating the growth of and preventing apoptosis of endometrial-like cells." (PMID 31291762, 2019). "Lastly, growth and angiogenic factors like Angiopoietin 1 (ANG-1), Angiostatin, Lipocalin-2, and ErbB3 were decreased in endometriosis patients, while IGF-1 was significantly elevated in diseased patients." (PMID 31333337, 2019). "In support of these findings, we also demonstrated that Igf-1 mRNA concentrations were elevated in peritoneal biopsies of mice with endometriosis, and levels were significantly attenuated when macrophages were depleted (P < 0.001)." (PMID 31291762, 2019). "We therefore suggest that in endometriosis lesions macrophage-derived IGF-1 contributes to pain by promoting nerve growth in lesions and by sensitizing nerves by enhancing nociceptive gene expression." (PMID 31291762, 2019). "We also confirmed expression of Igf-1 in F4/80+ macrophages in mouse endometriosis lesions using immunofluorescence." (PMID 31291762, 2019). "MCP-1, Rantes, IGF-1, and IL-8 are additionally involved in developmental or reproductive processes such as menstruation, pregnancy, and endometriosis." (PMID 28763032, 2017). "These functions may contribute to the maintenance and progression of ectopic endometrial lesions, highlighting IGF1-Ec as a potential therapeutic target or biomarker for late-stage endometriosis." (PMID 39796756, 2025). "The coordinated action of VEGF, IGF1/2 and H19 factors influences the development of endometriosis." (PMID 38791310, 2024). "Numerous studies have shown increased concentrations of interleukins (IL-1, IL-6, IL-8, and IL-33), tumor necrosis factor-alpha, insulin-like growth factor 1, and vascular endothelial growth factor in endometriosis patients, among endometriosis lesions and peritoneal fluid." (PMID 39136014, 2024). "Elevated levels of VEGF expressioncorrelate with decreasedlevels of IGF1 and H19 in endometriosis." (PMID 38791310, 2024).
endometriosis (continued). "The production of proinflammatory cytokines may occur as a result of disease-modified macrophages producing IGF-1, as high concentrations of IGF-1 were found in the peritoneal fluid of people with endometriosis." (PMID 38002684, 2023). "We hypothesized that IGF-1 isoforms may exhibit different expression profiles in the different forms of endometriosis, affecting their phenotype, aggressiveness, and histological features." (PMID 38275748, 2023). "Amongst the strengths, we could highlight that we have assessed the level of expression of all three IGF-1 isoforms in actual, surgically excised, endometriotic tissue of all endometriosis subtypes." (PMID 38275748, 2023). "This study identified novel associations with circulating metabolic and endocrine biomarkers (such as insulin-like growth factor 1 (IGF-1), and lower sex hormone binding globulin), and reported novel associations between longer telomere length and increased sarcoma risk and endometriosis." (PMID 36980881, 2023). "IGF1 was found in a GWAS of endometriosis in East Asian and European populations." (PMID 37626707, 2023). "In addition, it has been reported that IGF-1 protein concentration is increased in the peritoneal fluid of patients with endometriosis compared to control women." (PMID 35459174, 2022). "Besides, we showed higher gene and/or protein expression of IGF‐1 by PBMCs and PFMCs in endometriosis patients compared with controls." (PMID 36259314, 2022). "Decreased H19 expression in endometriosis lesions probably decreased IGF1 and IGF2 expression." (PMID 35459174, 2022). "In addition, IGF-1 concentration in peritoneal fluid of patients with endometriosis are significantly higher than that of normal controls." (PMID 36523599, 2022). "Therefore, in our study, decreased H19 expression probably reduces expression of IGF1 and thus decreased IGF1 signaling, leading to reduced stromal cell proliferation rate in endometriosis patients." (PMID 35459174, 2022). "In addition, IGF1 was downregulated in the eutopic endometrium of women with endometriosis compared to the control endometrial samples, whereas increased IGF1 expression in fibrotic peritoneal adhesions was observed." (PMID 35459174, 2022). "Macrophages have been implicated in other processes such as angiogenesis, promoting cellular proliferation of ectopic lesions, and modulating insulin-like growth factor-1 (IGF-1) which enhances nerve sensitization and increased pain scores in endometriosis animal models." (PMID 36008949, 2022). "IGF-1 is another important factor involved in the growth and proliferation of ESCs, which, along with increased estrogen receptor B and aromatase expression, lead to the progression of endometriosis." (PMID 34930225, 2021). "Furthermore, we evaluated the expression of MCP-1, HGF, and IGF-1 by peritoneal fluid mononuclear cells (PFMCs), peripheral blood mononuclear cells (PBMCs), and ESCs in women with endometriosis compared to controls." (PMID 34930225, 2021). "Macrophages treated with peritoneal fluid from women with endometriosis exhibit an up regulation of IGF-1 at the mRNA level, and mechanistically macrophage-derived IGF-1 increased the growth of embryonic rat dorsal root ganglion explants and this was reversed by an IGF-1 inhibitor." (PMID 32038499, 2020). "Thus, the neurotrophic effects of PF and macrophages in endometriosis are at least in part mediated by IGF-1." (PMID 31291762, 2019). "IGF-1 is also an obvious serum marker for late-stage endometriosis." (PMID 31505803, 2019). "We confirmed expression of Igf-1 in lesion-resident macrophages in women with endometriosis and mice with induced endometriosis, and we hypothesized that macrophage-derived Igf-1 is likely to play a key role in the pathogenesis of the disease." (PMID 31291762, 2019).
endometriosis (continued). "Additionally, the interaction between PFAS and insulin-like growth factor 1 (IGF1) may exacerbate the metabolic-inflammatory-proliferative vicious cycle, further driving the progression of endometriosis." (PMID 41492385, 2025). "Moreover, the interaction between PFAS and IGF1 may further exacerbate the metabolic-inflammatory-proliferative cycle, driving the progression of endometriosis." (PMID 41492385, 2025). "Macrophage-derived IGF-1 may be a key factor involved in the production of pain in endometriosis." (PMID 38791310, 2024). "Our results are consistent with our primary hypothesis that differential expression of IGF-1 isoforms in the different endometriosis subtypes may indicate that DIE and simple ovarian endometriosis should be considered as lesions developing under different pathogenetic mechanisms." (PMID 38275748, 2023). "Thus, we hypothesized that macrophage-derived IGF-1 might be a key factor involved in producing pain in endometriosis." (PMID 31291762, 2019). "The concentration of macrophage-derived IGF-1 is also elevated in the peritoneal fluid of patients with endometriosis, with a positive correlation between IGF-1 concentration and pain score, possibly because IGF-1 enhances nerve sensitization and neurogenesis." (PMID 39894821, 2025). "Immunohistochemistry was used to assess PRL-R and GH hormones, as well as IGF1 and IGF2 expressions, in normal endometrium and endometriosis tissues." (PMID 40076699, 2025). "Additionally, another study focusing on conditions like endometriosis underscored the dynamic interplay between IGF1 isoforms and oestrogen-sensitive tissues, shedding light on hormone-regulated pathways that may also influence EC progression and therapeutic approaches." (PMID 39796756, 2025). "IGF1 and IGF2 showed significantly higher expression in both epithelium and stroma of controls compared to endometriosis samples." (PMID 40076699, 2025). "The work of scientists from Iran has shown that the expression of the VEGF, IGF1, IGF2 and H19 lncRNA genes and the epigenetic changes of H19 lncRNA play a dynamic role in the pathogenesis of endometriosis." (PMID 38791310, 2024). "It was noted that the expression profiles of the H19, IGF1 and IGF2 genes werereduced in eutopic and ectopic endometrial tissues of patients with endometriosis compared to control tissues." (PMID 38791310, 2024). "Inflammatory cytokines (interleukin-1β (IL-1β), interleukin-6 (IL-6), insulin-like growth factor (IGF-1) and tumour necrosis factor-α (TNF-α) are observed to be at a higher concentration in the peritoneal fluid of people with endometriosis." (PMID 38002684, 2023). "Findings of this study showed that VEGF, IGF1, IGF2 and H19 lncRNA genes expression and epigenetic alterations of H19 lncRNA have dynamic role in the pathogenesis of endometriosis." (PMID 35459174, 2022). "The epithelium of the endometriosis lesion expresses high levels of IGF-1R and c-MET, the receptor for IGF1/2 and HGF, respectively." (PMID 35740424, 2022). "In this study, 1,25(OH)2D3 treatment significantly reduced the protein expression of MCP‐1, HGF, and IGF‐1 in PBMCs and PFMC of endometriosis patients at 48 h." (PMID 36259314, 2022). "Genes expression profile of H19, IGF1 and IGF2 was decreased in eutopic and ectopic endometrial tissues of endometriosis group, compared to the control tissues." (PMID 35459174, 2022). "In the present study, we evaluated and compared expression levels of H19 RNA factor and angiogenic (VEGF) and proliferative (IGF1, IGF2) genes in endometrium of non-endometriosis women in comparison with eutopic and ectopic tissues of endometriosis women." (PMID 35459174, 2022). "The results showed that expression of H19, IGF1 and IGF2 genes was decreased in eutopic and ectopic endometrial tissues of endometriosis group in comparison with control group." (PMID 35459174, 2022). "Therefore, IGF-1 might be one of the most critical factors in women with endometriosis." (PMID 34930225, 2021).
endometriosis (continued). "Estrogen has synergistic effects with IGF-1/VEGF and sometimes enhance the effects of IGF-1/VEGF on ectopic endometrial cells proliferation and mitosis, which possibly ended with endometriosis." (PMID 26945395, 2016). "However, it is not known whether the expressions of Igf1r and/or Igf1 are altered in the eutopic endometrium of women with endometriosis and if so, what the underlying mechanism might be." (PMID 26089099, 2015). "IGF1 and IGF2 play roles in cell proliferation and differentiation, suggesting dysregulation of these processes may occur in endometriosis." (PMID 39198675, 2024). "In addition, IGF-1 is overexpressed in women with endometriosis, favoring invasiveness, proliferation, decreased apoptosis, and angiogenesis on ectopic cells in conjunction with HGF and IGF-1." (PMID 39273667, 2024). "Mechanistically, macrophage-derived IGF-1 promotes sprouting neurogenesis and nerve sensitization in vitro and the IGF-1 receptor inhibitor Linsitinib reverses the pain behavior observed in mice with endometriosis." (PMID 37242543, 2023). "It should be stressed that the potential differential expression of IGF-1 isoforms in the different subtypes of endometriosis has not been studied to date." (PMID 38275748, 2023). "Previous studies have also shown that women diagnosed with endometriosis had higher concentrations of IGF-1 and NGF in the peritoneal fluid than women without endometriosis." (PMID 36879305, 2023). "Such treatment did not significantly change IGF‐1 gene expression in PBMCs of patients with and without endometriosis compared with untreated controls at 48 h." (PMID 36259314, 2022). "Furthermore, IGF-1 and HGF levels are higher in peritoneal fluid of women with endometriosis compared with the healthy women." (PMID 35207581, 2022). "AEBP1 and HOXB6, together with IGF-1, CYP11A1, MMP-2, CC2D2A, IER3, STX18, maybe staging markers for endometriosis." (PMID 36532015, 2022). "According to our literature review, no studies have ever been done on the production of IGF-1 by PFMCs and PBMCs in patients with endometriosis." (PMID 34930225, 2021). "Results obtained showed that the IGF-1 level in serum and PF in women with endometriosis was higher than in women without endometriosis (P < 0.05) (Figs. 3Aa and Ab)." (PMID 34930225, 2021). "In this study, we compared the concentrations of MCP-1, HGF, and IGF-1 in serum and PF of patients with and without endometriosis." (PMID 34930225, 2021). "These unclear data on MCP-1, HGF, and IGF-1 expression, hinder the understanding of the physiologic role of signaling in women with endometriosis, and no comprehensive study has examined all of the involved cells in endometriosis concurrently." (PMID 34930225, 2021). "IGF-1 gene expression by PBMCs in endometriosis patients was significantly higher than in women without endometriosis (P < 0.05)." (PMID 34930225, 2021). "Insulin-like growth factor-1 (IGF-1) has been increased in stages III–IV of endometriosis, but not in stages I–II." (PMID 32143439, 2020). "PF concentrations of IGF-1 have previously been shown to be elevated in patients with endometriosis compared with those without, and we confirmed this in the current study." (PMID 31291762, 2019). "IGF-1 protein concentration was significantly elevated in the PF of women with endometriosis compared with those without disease (P < 0.05) regardless of cycle phase." (PMID 31291762, 2019). "We also found that concentrations of IGF-1 in PF positively correlated with patient-reported pain scores (collected prior to surgery) in women with pelvic pain but no endometriosis and women with endometriosis and pelvic pain (P < 0.05)." (PMID 31291762, 2019). "In endometriosis lesions recovered at surgery from women during the secretory (progesterone-dominated) phase, we could detect macrophages (CD68) that coexpressed IGF-1 using dual immunofluorescence." (PMID 31291762, 2019).
endometriosis (continued). "Similarly, genes shared between endometriosis, uterine fibroids, ovarian cancer, migraine and depression (RHOA, FOXP1, ESR1, WNT4, GREB1, FSHB), and endometriosis, migraine and asthma (IGF1, SMAD3, MFHAS1), were enriched in hormone receptor signalling and inflammation pathways, respectively." (PMID 37159502, 2023). "However, the reducing effect of vitamin D treatment on IGF‐1 protein expression was more remarkable in PBMCs of endometriosis patients at 24 h (p < 0.05; data not shown)." (PMID 36259314, 2022). "According to our knowledge, this study is the first study to investigate the effect of 1,25(OH)2D3, the active form of vitamin D, treatment on MCP‐1, HGF, and IGF‐1 gene and protein expression in PBMCs, PFMCs, and ESCs of patients with and without endometriosis." (PMID 36259314, 2022). "The present study was designed to elucidate VEGF, IGF1, IGF2 and H19 lncRNA genes expression and epigenetic alterations of differentially methylated region (DMR) of H19 (H19-DMR) regulatory region in endometrial tissues of patients with endometriosis, in comparison with control women." (PMID 35459174, 2022). "Also, no obvious difference was detected among the IGF-1 serum concentrations in the different phases of the menstrual cycle of women with endometriosis and controls." (PMID 34930225, 2021). "In this case–control study, 24 women with and without endometriosis were studied for the relative expression of VEGF, IGF1, IGF2 and H19 lncRNA genes using real-time polymerase chain reaction (PCR) technique." (PMID 35459174, 2022). "In this case, resveratrol biological effect in terms of decrease in IGF-1 and HGF protein production was reported for both eutopic and ectopic endometrial stromal cells from women with endometriosis but not for cells from controls." (PMID 34444692, 2021).